RETN (resistin)
Diseases named in the same sentence as RETN in open-access papers (continued):
Sharing a sentence is not in itself a finding about the gene and the disease.
endothelial dysfunction (continued). "Endothelial dysfunction and/or pro-inflammatory effects could represent, thus, the link between higher resistin serum levels and increased prevalence of cardiovascular diseases in humans." (PMID 17479165, 2007). "NF-κB plays an important role in resistin (RETN) -induced bone remodeling, hyperglycemia-induced increase in RETN expression, in vivo development of IR, stimulation of pro-inflammatory cytokines in macrophages and peripheral blood mononuclear cells, and endothelial dysfunction." (PMID 36397950, 2022). "Moreover, our data showed that resistin levels correlated with inflammatory and endothelial dysfunction markers in T2DM women, suggesting that the association of resistin with CHD risk may be mediated by the inflammatory process." (PMID 34496965, 2021). "It appears that the treatment of obese rats with ZnONPs inhibits the progression of endothelial dysfunction, as evidenced by a reduction in the aortic tunica thickening, fibroid necrosis in the aorta, foam cells, and plasma levels of MCP-1, resistin, and CRP." (PMID 37749096, 2023). "In contrast, resistin, primarily released by activated monocytes, peaks slightly later (24–48 h) and mirrors ongoing monocyte/macrophage activation and endothelial dysfunction rather than acute tissue necrosis." (PMID 41226718, 2025). "Through its engagement with key receptors, notably TLR4 and CAP-1, resistin activates a cascade of proinflammatory signaling pathways, including NF-κB and MAPK, which drive endothelial dysfunction, promote leukocyte adhesion and migration, and initiate early atherosclerotic processes." (PMID 41347124, 2025). "High plasma resistin levels were observed in CVD patients, and its function has been related to vasodilation, and endothelial dysfunction, indicating that resistin might be involved in the regulation of blood pressure." (PMID 28525369, 2017). "Although previous studies suggested that resistin caused endothelial dysfunction via activated SOCS3 and JAK/STAT3 pathway, the upstream mechanisms underlying resistin’s action are not fully clear." (PMID 24526524, 2014). "Adipokines are involved in glucose metabolism (e.g., adiponectin, leptin, resistin, visfatin, and PAI-1), inflammation (e.g., resistin and leptin), reducing inflammation (e.g., adiponectin), coagulation (e.g., PAI-1), endothelial dysfunction (e.g., PAI-1), and feeding behavior (e.g., leptin)." (PMID 28552966, 2017).
psoriasis (52 papers, 2007 to 2025). An autoimmune condition characterized by red, well-delineated plaques with silvery scales that are usually on the extensor surfaces and scalp. "Our study similarly showed elevated resistin levels in the children with psoriasis, which confirms its role in predisposing pediatric patients to cardiovascular and metabolic complications." (PMID 40095687, 2025). "In our study, the statistical analyses revealed an association between resistin levels and psoriasis severity, as measured by the PASI and BSA scores." (PMID 40095687, 2025). "The research supports the conclusion that viral infections (especially HSV and HIV) are closely associated with increased resistin levels in patients with psoriasis." (PMID 40724556, 2025). "The highest prevalence of viral co-infections was in patients with increased resistin levels, illustrating the association of resistin with inflammation and viral activity in psoriasis." (PMID 40724556, 2025). "Leptin as well as resistin, is involved in Foxp3 + regulatory T-cell (Treg) deficiency in psoriasis, which lead to chronic activation of effector and memory T cells." (PMID 33927259, 2021). "Statistically significant decrease in serum resistin proves that biologic therapy not only provide clinical improvement but also affects the systemic inflammation associated with psoriasis and this effect persists with long-term therapy." (PMID 33927259, 2021). "At the same time, there were also suggestions that increased levels of resistin were associated with increased severity of psoriasis." (PMID 31316526, 2019). "Consistent with this view, serum levels of resistin are positively associated with psoriasis severity, with higher serum resistin levels found in more advanced stages of psoriasis." (PMID 25980409, 2015). "The major result of the meta-analysis revealed a statistically significant association between serum resistin levels and psoriasis (SMD = 2.22, 95%CI: 1.14-3.29, P < 0.001)." (PMID 25980409, 2015). "A positive association between resistin serum levels and psoriasis was identified in this meta-analysis (SMD = 2.22, 95%CI: 1.14-3.29, P < 0.001)." (PMID 25980409, 2015). "Further, subgroup analysis by sample size indicated a statistically significant association between resistin levels and psoriasis in both large sample size and small sample size subgroups (both P < 0.05)." (PMID 25980409, 2015). "These viral infections in conjunction with the examination of resistin can help provide useful information for diagnostic, treatment, and management options for psoriasis, particularly in individuals who have viral infections existing alone with psoriasis." (PMID 40724556, 2025). "Conversely, resistin and leptin, which were modestly upregulated in this study, are known to promote Th1 and Th17 immune responses and have been implicated in systemic inflammation and psoriasis severity." (PMID 39769200, 2024). "It is main value is to demonstrate that there is an association of resistin levels in psoriasis patients, mainly in those with comorbidities and that the comorbidities are, probably, the main target of treatment to avoid elevation of this serum adipocytokine in this setting." (PMID 37355349, 2023). "Psoriasis is a protean disease associated with several comorbidities that may have increased levels of adiponectin such as resistin." (PMID 37355349, 2023). "However, published studies on the association of resistin and psoriasis also had contradictory results." (PMID 31316526, 2019). "Interestingly, resistin has been shown to be associated with psoriasis, AD, AN, and Behçet disease." (PMID 31824416, 2019). "In inflammatory state underlying psoriasis, resistin produced mainly by monocytes and macrophages in adipose tissue, could stimulate the secretion of pro-inflammatory cytokines, TNF-α and IL-12, by monocytes in NF-kB-dependent manner." (PMID 29416693, 2018).
psoriasis (continued). "Interestingly, psoriasis is associated with overweight and with increased serum C-reactive protein, leptin and resistin levels." (PMID 25980409, 2015). "Therefore, in the present meta-analysis, we evaluated the relationship between serum resistin levels and psoriasis in order to test the feasibility of using serum resistin levels as diagnostic and prognostic tool for psoriasis." (PMID 25980409, 2015). "Bearing in mind that resistin plays a role in promoting pro-inflammatory pathways, its elevated level may also indicate an increased risk of other inflammatory diseases in patients with psoriasis." (PMID 40095687, 2025). "Thus, resistin, which is elevated in a minority of patients with moderate-severe psoriasis, may be more linked to mechanisms associated with RDW elevation than MPO, which may simply reflect skin release." (PMID 31936662, 2020). "Determining resistin levels in psoriasis patients has a good amount of scientific value and practical utility." (PMID 40724556, 2025). "A weak but statistically significant positive correlation was found between resistin levels and psoriasis severity, as measured by the PASI (Spearman’s rho = 0.26, p = 0.01) and BSA (Spearman’s rho = 0.23, p = 0.02)." (PMID 40095687, 2025). "Further studies are needed to investigate the relationship between selected metabolic and inflammatory biomarkers and psoriasis, with special consideration given to resistin as a marker of disease severity in larger cohorts of patients." (PMID 40095687, 2025). "This provides a strong rationale for reviewing both viral serologies and inflammatory biomarkers like resistin in a patient with worsening psoriasis." (PMID 40724556, 2025). "Since both psoriasis and viral infection involve significant immune activation and chronic inflammation, there is a need to investigate the prevalence of viral infections in psoriasis patients with elevated resistin and CRP levels." (PMID 40724556, 2025). "In this study, we observed elevated levels of inflammatory markers such as homocysteine, pentraxin 3, resistin, and leptin as well as a reduced levels of anti-inflammatory adiponectin in pediatric psoriasis patients compared to healthy controls." (PMID 40095687, 2025). "In psoriasis, resistin is involved in the disease’s progression and development via the release of pro-inflammatory cytokines including IL-6, IL-2, and TNF-α." (PMID 40724556, 2025). "Higher resistin levels were correlated with more severe disease, which implies that resistin is a potential marker of psoriasis severity." (PMID 40095687, 2025). "On the contrary, leptin, visfatin and resistin appear to be positively correlated with psoriasis activity." (PMID 40584532, 2025). "The research link between resistin and viral seropositivity in psoriasis is important, as it improves understanding of how viral infections exacerbate psoriasis." (PMID 40724556, 2025). "The research investigates the role of resistin in the immune response of patients with psoriasis, especially its modulation of the level and progression of viral co-infection with HSV, HIV, and HCV." (PMID 40724556, 2025). "Further studies are needed to determine the role of resistin and its correlation with clinical severity of psoriasis." (PMID 40095687, 2025). "The research can address existing knowledge gaps and enhance the understanding of the relationship between psoriasis and viral infections, while also evaluating the role of resistin in this interaction." (PMID 40724556, 2025). "Its resistin implications can also be researched through its interaction with immune cells and inflammatory mediators that promote psoriasis." (PMID 40724556, 2025). "Adipose tissue acts as an endocrine organ, resulting in the formation of cytokines associated with both psoriasis and NAFLD (adipocytokines, adipokines (leptin and resistin) TNF-α, and IL-6)." (PMID 38473907, 2024).
psoriasis (continued). "In the first step of our study, we compared the plasma concentrations of adiponectin, leptin, and resistin between patients with psoriasis and healthy control subjects." (PMID 36675592, 2023). "Patients with psoriasis had higher resistin levels (p = 0.009) and worse cIMT (p = 0.0002) than controls." (PMID 37355349, 2023). "Previous studies have shown elevated plasma resistin levels in patients with psoriasis, which correlated with disease activity parameters." (PMID 36675592, 2023). "The concentrations of leptin and resistin were higher in patients with psoriasis than in the control group, while adiponectin concentrations were lower." (PMID 36675592, 2023). "In our study, we found increased plasma concentrations of leptin and resistin in patients with psoriasis, while adiponectin levels were significantly lower than in healthy subjects." (PMID 36675592, 2023). "The results of our study confirm the role of adiponectin, leptin, and resistin in the pathogenesis of psoriasis." (PMID 36675592, 2023). "Serum resistin concentrations were significantly higher in psoriasis patients than that of healthy individuals." (PMID 37546687, 2023). "A meta-analysis including nine case-control studies with Caucasian and Asian patients suggested that resistin levels were markedly higher in psoriasis patients than controls." (PMID 37355349, 2023). "The plasma concentrations of resistin were significantly increased in patients with psoriasis compared to healthy controls (p = 0.02)." (PMID 36675592, 2023). "Our study also found that elevated plasma resistin levels in patients with psoriasis correlated with the DLQI index." (PMID 36675592, 2023). "Adiponectin has been shown to have a protective effect on the development of psoriasis, while leptin and resistin exert pro-inflammatory effects." (PMID 36675592, 2023). "Our study examined plasma concentrations of adiponectin, leptin, and resistin in patients with psoriasis." (PMID 36675592, 2023). "The results of studies suggest that resistin plays an important role in the development of psoriasis by affecting inflammatory factors such as TNF-α and reducing the population of Foxp3+ Treg cells." (PMID 36675592, 2023). "In the context of psoriasis, plasma levels of resistin are noticeably elevated when compared to healthy individuals." (PMID 38035065, 2023). "The adipokine milieu in patients with psoriasis is similar to that of prediabetic subjects, who present with lower levels of adiponectin and increased levels of leptin and resistin compared to healthy controls." (PMID 36012327, 2022). "A similar trend has been observed for other adipokines in psoriasis, with an increase in those with proinflammatory effects, including resistin, chemerin, and visfatin, and a decrease in those with anti-inflammatory effects, such as omentin." (PMID 36012327, 2022). "Serum levels of resistin are higher, while adiponectin lower in psoriasis patients in comparison with healthy controls and correlate with psoriasis severity, therefore, can be used as potential biomarkers for psoriasis development and treatment effectiveness." (PMID 33927259, 2021). "Visfatin and resistin were lower in psoriatics (p < 0.0001) and in diabetics with psoriasis (p < 0.001 and p < 0.0001, respectively) than diabetics." (PMID 33834030, 2021). "Higher levels of resistin have been observed in psoriasis patient and its serum concentration was correlated with the severity of skin lesions." (PMID 33927259, 2021). "Mean serum resistin level in patients with psoriasis prior to treatment with adalimumab was significantly higher than in the control group (p = 0.0289)." (PMID 33927259, 2021). "Higher leptin and resistin and lower adiponectin concentrations in psoriasis can be a proof of close relationship between skin inflammation and metabolic status in psoriasis patients." (PMID 33927259, 2021).
psoriasis (continued). "In our study resistin serum level in psoriasis patients was significantly higher than in control group and declined during biologic therapy." (PMID 33927259, 2021). "Visfatin and resistin were decreased in psoriatics (p < 0.0001 for both) and in diabetics with psoriasis (p < 0.001 and p < 0.0001, respectively) while a significantly reduction of vaspin was observed only in psoriatics (p < 0.001) compared with diabetics." (PMID 33834030, 2021). "Adiponectin and visfatin were lower, whereas resistin and vaspin were higher in diabetics, psoriatics and diabetics with psoriasis compared with controls (p < 0.0001 for all)." (PMID 33834030, 2021). "In a recent meta-analysis of nine case-control studies, containing 421 psoriasis patients and 348 healthy controls, serum resistin levels were higher in psoriasis patients of both Asian and Caucasian origin." (PMID 33499118, 2021). "Elevated levels of resistin were consistently observed in the circulation of psoriasis patients and positively correlated with the PASI score." (PMID 33260746, 2020). "In a dataset of 75 patients in whom RDW and resistin levels were obtained, almost half of the psoriasis patients had elevated resistin, and nine patients had elevated RDW, which represented 24% of the resistin high subset." (PMID 31936662, 2020). "In patients with psoriasis, elevated levels of leptin, chemerin, visfatin and resistin have been found, with decreased levels of protective adipokines: adiponectin and omentin." (PMID 33187195, 2020). "Studies have shown that resistin was also found to be present in higher concentrations in patients with psoriasis compared to control population." (PMID 31316526, 2019). "A recent meta-analysis attempted to demystify these inconsistencies and showed that indeed, higher serum concentrations of resistin level positively correlated with psoriasis disease progression." (PMID 31316526, 2019). "All concluded that leptin and resistin had higher levels in patients with psoriasis, compared to the healthy control population, and that adiponectin levels were lower in psoriasis patients than in healthy patients." (PMID 31275060, 2019). "Elevated levels of leptin and resistin and lower levels of adiponectin in serum adjusted for BMI have been shown in patients with PsA and psoriasis in comparison with healthy controls." (PMID 30635024, 2019). "With respect to leptin and resistin, both of these adipokines are present in high levels in obese persons with psoriasis." (PMID 31275060, 2019). "The pooled serum levels of TNF-α, IFN-γ, IL-2, IL-6, IL-8, IL-18, IL-22, chemerin, lipocalin-2, resistin, sE-selectin, fibrinogen and C3 were higher in psoriasis patients compared with healthy controls (all P < 0.05)." (PMID 29416693, 2018). "In contrast, a couple of studies on Turkish patients with systemic sclerosis, and Iranian patients with psoriasis, showed higher resistin levels in patients compared to control groups." (PMID 29584687, 2018). "Serum levels of TNF-α, IFN-γ, IL-2, IL-6, IL-8, IL-18, IL-22, chemerin, lipocalin-2, resistin, sE-selectin, fibrinogen, complement 3, and adiponectin correlate with psoriasis and can be used as potential biomarkers for psoriasis and response to the treatment." (PMID 29416693, 2018). "Subsequently, we evaluated the association between serum levels of adipokines (adiponectin, omentin, chemerin, visfatin, lipocalin-2, and resistin) and psoriasis." (PMID 29416693, 2018). "We found that serum levels of three proinflamatory adipokines (chemerin, lipocalin-2 and resistin) were increased, while serum levels of one anti-inflammatory adipokine, adiponectin, were decreased in psoriasis patients." (PMID 29416693, 2018). "The presented data support general opinion that cytokines produced by adipocytes (adiponectin, leptin, and resistin) are involved in the pathogenesis of MS as well as in the pathogenesis of psoriasis." (PMID 28097156, 2016).